TGFBI (transforming growth factor beta induced)
Diseases named in the same sentence as TGFBI in open-access papers (continued):
Sharing a sentence is not in itself a finding about the gene and the disease.
breast carcinoma (continued). "Next, we validated the prognosis of TGFBI using breast cancer tissue microarray." (PMID 38245723, 2024). "Next, we determined the prognostic relevance of TGFBI methylation levels in breast cancer." (PMID 38245723, 2024). "A previous study demonstrated that TGFBI could induce cellular senescence in mesothelioma and breast cancer cells." (PMID 38412321, 2024). "Consequently, further studies are warranted to elucidate the identity of this transcription factor and its role in either repressing or promoting TGFBI expression in renal and breast cancer." (PMID 38297161, 2024). "However, reduced TGFBI expression has been observed in some malignancies, such as breast cancer and lung cancer compared with normal tissues." (PMID 35083181, 2022). "Notably, high TGFBI expression was significantly associated with poor DMFS, OS, post-progression survival (PPS), and RFS in breast cancer (p < 0.01)." (PMID 34671645, 2021). "FN1 (fibronectin 1) acts as a ceRNA for miR-200c in the canonical SNAIL-ZEB-miR200 pathway in breast cancer cells, whereas TGFBI (transforming growth factor-beta-induced) is a transcript that is highly induced during EMT in lung cancer cells, which acts as the ceRNA for miR-21 to modulate EMT." (PMID 31947678, 2020). "Taken together, our findings suggest that TGFBI may be used as a prognostic factor in breast cancer and open potential new opportunities for combinatorial therapies." (PMID 33080107, 2020). "The mechanism by which TGFBI regulates tumour hypoxia in breast cancer and whether this effect is direct or indirect remains unclear." (PMID 33080107, 2020). "TGFBI protein expression is reduced in breast carcinoma cells." (PMID 25889002, 2015). "Engineered mesothelioma cell clones (T2804, T2806, and T2807) and breast cancer cell clones (T23108, T23109, and T23113) ectopically expressing TGFBI were generated from their respective parental tumor cell lines, which only contained trace amounts of TGFBI." (PMID 22695319, 2012). "Moreover, the prognosis of TGFBI was validated in 139 Chinese breast cancer patients." (PMID 38245723, 2024). "Moreover, TGFBI was correlated with the prognosis and immune infiltrations of breast cancer." (PMID 38245723, 2024). "Additionally, deletion of ZEB1 or TGFBI (BIG-H3) in breast cancer cells enhanced sensitivity to PARP inhibitors, suggesting that CIN resistance mechanisms may represent potential therapeutic vulnerabilities." (PMID 39345336, 2024). "The high expressions of TGFBI in some cases of breast cancer may be induced by TGFβ." (PMID 38245723, 2024). "Also, TGFBI highly expressed breast cancer patients were with higher ki67 expressions." (PMID 38245723, 2024). "TGFBI expression could be detected in most breast cancer tissues." (PMID 38245723, 2024). "Furthermore, in GSE1456, GSE7390, GSE20685, GSE24450, and GSE158309 datasets, but not in TCGA-BRCA dataset, higher expression of TGFBI was associated with the shorted overall survival of breast cancer." (PMID 38245723, 2024). "Similarly, a previous study indicated that TGFBI may support cancer stem cell growth and tumor progression to metastasis in breast cancer (Fico and Santamaria-Martínez, 2020)." (PMID 34671645, 2021). "In addition, once the resistance is developed, demethylation of TGFBI with compounds that inhibit DNA methyltransferases could contribute to the sensitization of breast cancer cells to the trastuzumab treatment." (PMID 31277676, 2019). "Key genes, such as BSG, TGFBI, and ADAM17, were already shown as having well-established roles in breast cancer biology." (PMID 41374933, 2025). "Furthermore, combining the expression data of GSE2034, GSE2603 and GSE5327 datasets into a larger cohort, we found that in both ER negative and ER positive breast cancer patients, TGFBI higher expression was associated with the higher probability of lung metastasis." (PMID 38245723, 2024).
breast carcinoma (continued). "Once they are confirmed in the clinic, they can divide HER2-positive breast cancer into different subgroups, such as SH3BGRL, TGFBI methylation, and MEl-18." (PMID 37174034, 2023). "Data from The Cancer Genome Atlas (TCGA) database demonstrated upregulation of CCL8 and TGFBI and downregulation of HGF in breast cancer." (PMID 37884960, 2023). "Others, such as COL18A1, TGFBI, FGB, ITIH2, ITIH4, and TNC among others, were overrepresented in 3 of 4 signatures and also expressed in mammary carcinoma xenografts." (PMID 37098922, 2023). "Taken together, these data suggest that TGFBI in the ECM is an important driver of tumour‐ and metastasis‐initiating capacity in breast cancer." (PMID 33080107, 2020). "We identified two breast carcinoma tumor cells, T47D and MCF7, which demonstrated high DDR1 and low TGFBI, similar to BXPC3." (PMID 25369402, 2014). "In this study, an ectopic expression of TGFBI in two types of cancer cell lines, a mesothelioma cell line NCI-H28 and a breast cancer cell line MDA-MB-231 was found to have reduced the cellular growth, plating efficiency, and anchorage-independent growth." (PMID 22695319, 2012). "We analyzed impact of CTGF on other secretome analysis detected targets and could detect that reducing CTGF expression represses TGFBI, LOX and ZEB1 expression in mesenchymal transformed breast cancer cells." (PMID 33087801, 2020). "Our results in breast cancer also suggest a tumour‐promoting role of TGFBI, but they indicate that modulating TGFBI in breast cancer cells does not directly impact the CSC phenotype and therefore the metastatic potential of tumour cells." (PMID 33080107, 2020). "In breast cancer cells, neither the telomerase activity nor expression of p16 and p14 changed in response to re-expression of TGFBI." (PMID 22695319, 2012). "In contrast to decreased TGFBI that has previously been associated with DCIS, decreased CADM3, DPT, and NID1 have not previously been linked to breast cancer." (PMID 23236365, 2012). "However, the prognosis of TGFBI was not yet clear in breast cancer." (PMID 38245723, 2024).
lung carcinoma (27 papers, 2002 to 2025). "Our previous study reported that cancer stromal TGFBI expression was significantly associated with therapeutic resistance in patients receiving nivolumab for lung cancer." (PMID 37511547, 2023). "Our previous report showed that high stromal transforming growth factor-beta-induced protein (TGFBI) in lung cancer was associated with poor prognosis and therapeutic resistance to ICIs." (PMID 37511547, 2023). "For example, TGFBI loss or down-regulation has been observed in human lung carcinoma samples by immunohistochemistry." (PMID 25889002, 2015). "Loss of TGFBI expression has been associated with the tumorigenic phenotype of several carcinomas including lung cancer." (PMID 20509890, 2010). "Loss of TGFBI expression has been described in several cancers including lung carcinoma, and it has been suggested to act as a tumor suppressor gene." (PMID 20509890, 2010). "In relation to lung cancer, loss of TGFBI expression has been described in asbestos and radiation-exposed human bronchial epithelial cells and in human lung cancer samples." (PMID 20509890, 2010). "In summary, dense methylation of the TGFBI promoter was associated with invasiveness in prostate cancer and metastasis in lung cancer." (PMID 18834524, 2008). "In previous study, methylation of TGFBI promoter predicts dismal prognostic outcome and better chemotherapeutic response among lung cancer cases." (PMID 37083272, 2023). "Immunochemistry results showed the expression of TGFBI in lung carcinomas was lower than normal tissues." (PMID 33912443, 2021). "For instance, TGFBI has been suggested to have tumour suppressive activities in mesothelioma, breast, and lung cancer cells." (PMID 33080107, 2020). "Down‐regulation of TGFBI was observed in H460 and H1975 lung cancer cells, and of TIEG1 in H157 and H322 lung cancer cells." (PMID 26969027, 2016). "In our study, up‐regulation of TIEG1 was noted in H157 and H322 lung cancer cell lines, and up‐regulation of TGFBI was noted in H460 lung cancer cell line." (PMID 26969027, 2016). "Further studies to elucidate the association of Cul4A with TGFBI and TIEG1 in lung cancer cells are ongoing in our laboratory." (PMID 26969027, 2016). "Lung carcinoma cells transfected with a TGFBI-expressing construct fail to establish tumors in mice in vivo whereas empty vector-transfected cells do, indicating a suppressive effect of TGFBI on tumor formation." (PMID 25889002, 2015). "For example, TGFBI overexpression inhibits tumorigenesis and reduces the mobility of lung carcinoma cells." (PMID 25889002, 2015). "Overall, TGFBI methylation was present in 44.0% (22/50) of lung cancer specimens and 82.0% (41/50) of prostate cancer specimens." (PMID 18834524, 2008). "Our study revealed that dense TGFBI promoter methylation is correlated with the invasiveness of prostate cancers, and with the metastatic status of lung cancers." (PMID 18834524, 2008). "High TGFBI expression was associated with poor FP and OS but good PPS in lung cancer (p < 0.001)." (PMID 34671645, 2021). "In addition, miR-493-5p has been previously reported as prognostic marker for overall survival of patients with lung cancer, while miR-21 has been found to induce cell proliferation by targeting TGFBI." (PMID 33092114, 2020). "TGFBI was originally identified as a TGFβ-induced gene in lung carcinoma cells." (PMID 30084753, 2018). "On the contrary, lower expression of TGFBI was noted in H157 and H322 lung cancer cell lines, and up‐regulation of TIEG1 may account for increased sensitivity to gemcitabine after knockdown of Cul4A in these two cancer cell lines." (PMID 26969027, 2016). "In H460 lung cancer cell line, higher expression of TGFBI was noted compared to the expression of TGFBI in H157 and H322 lung cancer cell lines, which may account for increased sensitivity to gemcitabine after knockdown of Cul4A in H460 lung cancer cell line." (PMID 26969027, 2016).
lung carcinoma (continued). "Different expressions of TIEG1 and TGFBI in lung cancer cell lines after Cul4A knockdown or expression may indicate different pathways for gemcitabine chemosensitivity in different lung cancer cells." (PMID 26969027, 2016). "TIEG1 has been reported as a transactivator of TGFBI in renal cell carcinoma 38; however, the interaction between TIEG1 and TGFBI in lung cancer cells remains unclear." (PMID 26969027, 2016). "Increased TIEG1 was observed in H157 and H322 and increased TGFBI in H460 in lung cancer cells." (PMID 26969027, 2016). "Thus, we studied the expression of TIEG1 and TGFBI in Cul4A shRNA transfected stable lung cancer cells." (PMID 26969027, 2016). "The C-terminal fragment of TGFBI induces human osteosarcoma and lung carcinoma cell apoptosis." (PMID 25889002, 2015). "TGFBI has been discovered as a gene induced in the lung cancer cell line A549 by TGF-β." (PMID 26422603, 2015). "Fifty lung cancer patient samples were screened for TGFBI methylation by MSP." (PMID 18834524, 2008). "Dense methylation of the TGFBI promoter correlated with the extent of TGFBI gene silencing in tumor cell lines and was related to invasiveness of prostate tumors and metastatic status of lung cancer tumors." (PMID 18834524, 2008). "Among 50 lung cancer samples, 44.0% (22/50) harbored methylated CpG sites in the TGFBI promoter." (PMID 18834524, 2008). "Thus, TGFBI promoter methylation can be used as a potential prognostic marker for invasiveness and metastasis in prostate and lung cancer patients, respectively." (PMID 18834524, 2008). "Although we found that TGFBI expression was negatively correlated with CD8+ T cells, another study showed that both high stromal TGFBI expression and intratumoral CD8+ T cells infiltration were associated with poor prognosis and drug resistance in lung cancer patients." (PMID 34671645, 2021). "Additionally, knockdown of Cul4A increased expression levels of TGFBI in H460 lung cancer cells." (PMID 26969027, 2016). "Additionally, TGFBI-derived peptides could be used in the near future as adjuvants in lung cancer therapy." (PMID 20509890, 2010). "Therefore, cancer cells with a densely methylated TGFBI promoter may be prone to invasiveness in prostate cancer and metastasis in lung cancer." (PMID 18834524, 2008). "In summary, dense methylation of the TGFBI promoter correlates with gene silencing that in turn may promote an advanced tumorigenic phenotype, such as invasiveness in prostate cancer and metastasis in lung cancer." (PMID 18834524, 2008). "TGFBI has been reported to suppress tumor cell growth in NSCLC and other types of human lung cancers." (PMID 28231844, 2017). "Moreover, increased expression of p21, transforming growth factor (TGF)‐β inducible early gene‐1 (TIEG1) and TGF beta‐induced (TGFBI) was observed in lung cancer cells after Cul4A knockdown, which may be partially related to increased chemosensitivity to gemcitabine." (PMID 26969027, 2016). "Transforming growth factor beta-induced (TGFβI) gene, which is otherwise known as betaig-h3, was first identified through the induction of its expression by TGF-β in human lung carcinoma cell lines." (PMID 25950587, 2015). "In our study, different lung cancer cells showed different expressions of TIEG1 and TGFBI after Cul4A knockdown or expression, which may indicate different pathways for gemcitabine chemosensitivity in different lung cancer cells." (PMID 26969027, 2016). "Besides, recovery of TGFBI expression in lung cancer cell H522 lacking endogenous TGFBI protein leads to a significant decrease in cell growth and a significantly higher sensitivity to apoptotic induction." (PMID 33912443, 2021).
glioma (26 papers, 2012 to 2025). A benign or malignant brain and spinal cord tumor that arises from glial cells (astrocytes, oligodendrocytes, ependymal cells). "An important observation is that the expression of the transforming growth factor beta-induced (TGFBI) by tumor-associated macrophages promotes glioma stem cell maintenance and glioblastoma growth via integrin αvβ5-Src-Stat3 signaling." (PMID 37626776, 2023). "has discovered co-culture of naive T cell with glioma-associated MDMs can induce a differentiation into TGFBI and IL-10 secreted CD4+ Treg cell." (PMID 36761752, 2023). "TGFBI also inhibits cell adhesion, promotes cell migration in glioma cells and has been associated with the expression signature of mesenchymal GBM, the molecular subtype with the poorest prognosis." (PMID 36076905, 2022). "Previous studies indicate that TGFBI is associated with glioma proliferation and migration, as well as tumor malignancy." (PMID 34566988, 2021). "In glioma cells, a high TGFBI expression was associated with poor prognosis and phosphorylation of AKT and mTOR." (PMID 33921897, 2021). "Their results suggested that TGFBI has the potential to be a diagnostic marker and to serve as a target for the treatment of gliomas." (PMID 33553434, 2021). "The results revealed that CSF1R, TGFBI, and IDO1 serve as key nodes in the protein interaction network, suggesting their critical roles in glioma progression and tumor-associated inflammation." (PMID 40881678, 2025). "TGFBI (Transforming Growth Factor Beta Induced) plays a crucial role in maintaining glioma stemness and promoting tumor growth." (PMID 40881678, 2025). "The expression of EphA2 in GSC spheres was confirmed through IF, and a correlation between TGFBI and EphA2 in human glioma specimens was observed via IHC staining." (PMID 39346536, 2024). "To explore the role of TGFBI in gliomas, we conducted an analysis using the CCGA and TCGA databases." (PMID 39346536, 2024). "Further IHC analysis of human glioma specimens indicated a positive correlation between TGFBI and SOX2 expression level, as well as CD133." (PMID 39346536, 2024). "We found that TGFBI expression is higher in IDH wild-type (IDH wt) gliomas in comparison to IDH mutant gliomas." (PMID 39346536, 2024). "The Kaplan-Meier analysis of TGFBI expression in 76 gliomas indicated that higher expression denoted shorter survival time." (PMID 35673564, 2022). "These bioinformatics analyses suggested that TGFBI was the potential molecular preferentially secreted by M2-like TAMs in the glioma microenvironment." (PMID 35673564, 2022). "Our results indicated the critical role of TGFBI secreted by M2-like TAMs in GSC-driven glioma growth, adding credence to the importance of TGFBI across cancers." (PMID 35673564, 2022). "To investigate its serum range in glioma patients and the healthy cohort, we assayed serum TGFBI levels in 6 healthy controls and 52 glioma patients." (PMID 35673564, 2022). "Our clinical data accordingly demonstrates a positive correlation of the serum and CSF TGFBI levels with tumor malignancy and tumor burden of glioma patients." (PMID 35673564, 2022). "Expanded longitudinal studies of the serum and CSF TGFBI level measured prospectively in glioma patients are warranted for its potential application as a glioma circulating marker." (PMID 35673564, 2022). "In summary, our data demonstrated that TGFBI was secreted by M2-like TAMs, promoting the maintenance of GSCs and glioma growth through integrin αvβ5-Src-Stat3 signaling." (PMID 35673564, 2022). "Expression of a three-gene signature, comprised of TGFBI, IGFBP3, and CHI3L1, has previously been associated with glioma tumor cell invasion and migration and poor patient survival." (PMID 34539622, 2021). "RNAseq showed that TGFBI was upregulated in several cell lines, including kidney cancer, chondrosarcoma, upper aerodigestive tract cancer, glioma, osteosarcoma, thyroid cancer, liver cancer and mesothelioma cell lines." (PMID 34671645, 2021).